PRRG1 (proline rich and Gla domain 1)
Synonyms: PRGP1
Tractability: Antibody: its Gene Ontology location is reachable by antibodies, with high confidence; UniProt predicts a signal peptide or a membrane-spanning region; the Human Protein Atlas places it where antibodies can reach. PROTAC: ubiquitination databases record sites on it.
Gene: Protein-coding gene on chromosome X (37,349,309 to 37,492,702, forward strand). Ensembl gene ENSG00000130962.
Subcellular location: Membrane
Subcellular location (Human Protein Atlas): Plasma membrane; Vesicles; Nucleoplasm
Gene Ontology:
Molecular function: protein binding; serine-type endopeptidase activity; calcium ion binding
Biological process: blood coagulation; proteolysis
Cellular component: plasma membrane; extracellular region; membrane
Homologues: Orthologues: chimpanzee PRRG1 (99% identical), rabbit PRRG1 (96% identical), pig PRRG1 (96% identical), dog PRRG1 (94% identical), rat Prrg1 (94% identical), guinea pig PRRG1 (94% identical), mouse Prrg1 (93% identical), tropical clawed frog prrg1 (55% identical), zebrafish prrg1 (39% identical). Paralogues in human: PRRG3 (36% identical), PRRG4 (23% identical), OVCH2 (11% identical).
Diseases named in the same sentence as PRRG1 in open-access papers:
PRRG1 is named in the same sentence as 10 diseases in open-access papers, as found by Europe PMC text mining. Sharing a sentence is not in itself a finding about the gene and the disease. The quoted sentences say what the papers report.
pancreatic cancer (2 papers, 2025 to 2026). "In this study, we investigated the expression patterns, biological functions, and molecular mechanisms of Proline-rich γ-carboxylated Gla protein 1 (PRRG1) in pancreatic cancer pathogenesis." (PMID 42108282, 2026). "We verified the high expression of PRRG1 in pancreatic cancer tissue specimens and pancreatic cancer cell lines." (PMID 42108282, 2026). "In conclusion, our findings establish PRRG1 as a key driver of pancreatic cancer progression through PI3K/Akt pathway activation and KLF4-mediated transcriptional regulation." (PMID 42108282, 2026). "To investigate the expression profiles of PRRG1 in pancreatic cancer, we analyzed GEO datasets containing paired cancer and non‐cancerous specimens." (PMID 39843398, 2025).
atherosclerosis (1 paper, 2023). A disease characterized by the build-up of fatty material and calcium deposition in the arterial wall resulting in partial or complete occlusion of the arterial lumen. "Furthermore, a decrease in PRRG1 (as seen in 47,XXY) is associated with intima thickening in atherosclerosis." (PMID 36978128, 2023).
Cirrhosis (1 paper, 2023). A chronic disorder of the liver in which liver tissue becomes scarred and is partially replaced by regenerative nodules and fibrotic tissue resulting in loss of liver function. "The miR-17-92 cluster, which is upregulated in cirrhosis, is a well-characterized oncomiR due to its capacity to inhibit the expression of cAMP Responsive Element Binding Protein Like 2 (CREBL2), Proline Rich and Gla Domain 1 (PRRG1), and Netrin 4 (NTN4)." (PMID 38067261, 2023).
pancreatic ductal adenocarcinoma (1 paper, 2025). An infiltrating adenocarcinoma that arises from the epithelial cells of the pancreas. "Analysis of pancreatic ductal adenocarcinoma (PDAC) datasets, including transcription profiles, clinical data, and tissue microarrays, was conducted to evaluate PRRG1 expression and its clinical relevance." (PMID 39843398, 2025).
tumor (5 papers, 2018 to 2026). "Low-dose warfarin significantly suppressed the pro-tumorigenic effects and the PRRG1 overexpression-driven alterations in the tumor immune microenvironment." (PMID 42108282, 2026). "The result showed that PRRG1 overexpression significantly enhanced the in vivo tumour growth of PANC1 cells, which was clearly reversed by low‐dose warfarin." (PMID 39843398, 2025). "The increased tumour burden induced by Prrg1 overexpression was significantly attenuated after low‐dose warfarin treatment." (PMID 39843398, 2025). "Our study characterized PRRG1 as another Gla protein that played crucial roles in oncogenic tumour growth in PDAC, with its function dependent on the γ‐carboxylation of the Gla domain." (PMID 39843398, 2025). "We observed that anchorage‐independent growth and in vivo, tumour growth were more dramatically inhibited by PRRG1 knockdown cells as compared with that in the in vitro proliferation assay." (PMID 39843398, 2025). "Further, we established a subcutaneous tumour model by inoculating the control and PRRG1‐overexpression PANC1 cells to the NOD‐SCID mice." (PMID 39843398, 2025). "Prrg1 overexpression significantly promoted the orthotopic tumour growth of KPC1199luc, as indicated by the increased bioluminescent signals and the pancreas burden." (PMID 39843398, 2025). "The result demonstrated that the in vivo tumour growth of PDAC cells was evidently suppressed in PRRG1‐knockdown groups compared with the control group." (PMID 39843398, 2025). "In vivo, PRRG1 knockdown inhibited tumor growth and PI3K-Akt activation in subcutaneous xenograft models, while PRRG1 overexpression accelerated tumor progression." (PMID 42108282, 2026). "PRRG1 knockdown reduced PDAC cell proliferation, anchorage‐independent growth in vitro, and tumor growth in vivo." (PMID 39843398, 2025). "Moreover, a low dose of warfarin below the anticoagulant dosage, effectively blocks γ‐carboxylation of the Gla domain of PRRG1, reverses its regulation on KRAS and EGFR, and PDAC in vivo tumour growth." (PMID 39843398, 2025).
cancer (2 papers, 2011 to 2025). A tumor composed of atypical neoplastic, often pleomorphic cells that invade other tissues. "Predominant immunostaining of PRRG1 was detected and observed on the plasma membrane of cancer cells, with high PRRG1 expression positively correlated with poor survival." (PMID 39843398, 2025). "Moreover, we found that PRRG1 was nearly undetectable in normal pancreatic acinar cells or ductal cells while it was gradually upregulated in precursor lesions (pancreatic intraepithelial neoplasia, PanINs) and PDAC cancer cells." (PMID 39843398, 2025).
PRRG1 also shares sentences with these, for which no sentence is quoted: abortion (1 paper); breast carcinoma (1); gastric cancer (1); glioma (1).